E2F3 (E2F transcription factor 3)
Diseases named in the same sentence as E2F3 in open-access papers (continued):
Sharing a sentence is not in itself a finding about the gene and the disease.
prostate carcinoma (continued). "Given that prostate cancer is a highly heterogeneous tumor, somatic mutations of clinicopathologically significant E2Fs, including the E2F1, E2F2, E2F3, E2F5, and E2F6, were further investigated in PCa patients." (PMID 35531101, 2022). "MiR-200c was regulated by EZH2 through epigenetic repression in prostate cancer, and miR-200c directly controlled the expression of E2F3 by targeting 3′UTR." (PMID 36316365, 2022). "According to previous studies, high expression of E2F3 has been known to show poor prognosis in many human cancers such as human bladder and prostate cancer." (PMID 30487158, 2018). "Dyregulation of E2Fs expression have been interacted with a variety of types of cancers, and E2F3 has been found to be over-expressed in bladder, lung and prostate cancers." (PMID 27351135, 2016). "Evidence suggests that overexpression of E2F3 represents an oncogenic event during human bladder carcinogenesis and in many cases of prostate cancer." (PMID 22520446, 2012). "E2F3 is a member of the E2F transcription factor family that is over-expressed in bladder and prostate cancers." (PMID 20925909, 2010). "It regulates prostate cancer cells through the lncRNA H19/miR-194/E2F3 axis." (PMID 41157091, 2025). "All findings confirmed that the aberrant profiles of lncRNA H19, miR-194, and E2F3 might be correlated with prostate cancer." (PMID 37253635, 2023). "Our research intended to probe the regulatory relationship among Brevilin A, lncRNA H19, miR-194, and E2F3 and their influence on the biological behaviors of prostate cancer cells, and the mechanism of Brevilin A affecting lncRNA H19 expression in prostate cancer was investigated." (PMID 37253635, 2023). "Additionally, lncRNA H19 and E2F3 were more highly expressed in prostate cancer cell lines than in human prostate epithelial cells PrEC, whereas miR-194 expression exhibited the opposite result." (PMID 37253635, 2023). "LncRNA H19 and E2F3 were uplifted, whereas miR-194 was abated in prostate cancer cells and tissues." (PMID 37253635, 2023). "Consequently, Brevilin A dampened prostate cancer cell proliferation, migration, and invasion, suppressed the expressions of lncRNA H19 and E2F3, and enhanced miR-194 level." (PMID 37253635, 2023). "Meanwhile, regulating E2F1/E2F3/Caspase-3 axis may be one way that VA blocks stemness and advances apoptosis in prostate cancer cells." (PMID 36175803, 2022). "However, the overexpression of E2F3 is reported to correlate with poor overall survival in prostate cancer patients suggesting that the network correlation of this gene may be independent of any tumor phenotype." (PMID 37065756, 2023). "Furthermore, high E2F3 expression could reverse the regulatory effects of miR-194 mimics on DU145 cells, while E2F3 inhibition could eliminate the regulatory function of miR-194 inhibitors, suggesting that miR-194 could modulate prostate cancer cells via targeting E2F3." (PMID 37253635, 2023). "In summary, E2F1, E2F2, E2F3, E2F5, and E2F6 were found to be correlated with the malignant progression of prostate cancer." (PMID 35531101, 2022). "Overall, E2F1, E2F2, E2F3, and E2F5 were found to be correlated with the malignant progression of prostate cancer." (PMID 35531101, 2022). "Subsequently, we further investigated the alteration of immune cell components in samples with altered expressions of E2F1, E2F2, E2F3, E2F5, and E2F6 in prostate cancer based on TCGA." (PMID 35531101, 2022). "In a prostate cancer cell line, miR-20a directly inhibits the translation of the E2F1, E2F2 and E2F3 mRNA, and the endogenous E2F1, E2F2 and E2F3 bind to the promoter of the miR-17~92 cluster and activate its transcription." (PMID 27282946, 2016). "Because E2F3 interact with ARNT, we can infer the interactions between two dependent genes AKT3 and CHUK and map to their gene products, protein PKB and IKK in prostate cancer pathway." (PMID 20025723, 2009).
prostate carcinoma (continued). "Western blot and immunohistochemistry reflected that E2F3 was highly expressed in prostate cancer tissues as opposed to adjacent normal tissues." (PMID 37253635, 2023). "As a transcription factor, E2F3 directly targets IL-6 signaling and is involved in prostate tumorigenesis, and dysregulation of the E2F5/p38/SMAD3 circuitry has been found to reinforce the protumorigenic switch of TGFβ signaling in prostate cancer." (PMID 35531101, 2022). "Meanwhile, there are several genes which mediate the miR-34a induced tumor growth inhibition, such as BCL2, E2F3 and MYCN in neuroblastoma, mitogen-activated protein kinase kinase 1 (MEK1) in human chronic myelocytic leukemia cell line K562 and SIRT1 in prostate cancer PC3 cells." (PMID 22457788, 2012).
retinoblastoma (27 papers, 2007 to 2025). A malignant tumor that originates in the nuclear layer of the retina. "We quantified mRNA expression of candidate genes for proliferation (KIF14 and E2F3) in a large retinoblastoma tumor cohort and associated with disease phenotype." (PMID 19190782, 2009). "Retinoblastoma and bilateral retinoblastoma are diseases linked to E2F3." (PMID 39129166, 2025). "To determine which E2F transcription factors could be associated with upregulation of FA genes, we studied also the mRNA expression levels of activating E2F genes (E2F1, E2F2, E2F3) in RB1-mutated retinoblastoma and in basal breast tumors." (PMID 25161863, 2014). "Moreover, in a subtype of human retinoblastoma where Rb is already deficient, E2f-3 proteins are also overexpressed." (PMID 20808898, 2010). "Hence, our integrative bioinformatics and in vitro validation results suggest that the RB1 gene loss in retinoblastoma patients could provoke epigenetic events which in turn dysregulate the expression of E2F3 and thus promote Rb development in retinal cells." (PMID 35359459, 2022). "Phosphorylation of rb is PTH-dependent and E2F3, which is a candidate for tumor progression in retinoblastoma belongs to the group of E2F which is targeted and stimulated by PTH." (PMID 39141058, 2024). "For example, lncRNA transcript RBAT1 recruits hnRNPL to the promoter of oncogene E2F3 to ci-activate its transcription, resulting in the tumorigenesis of retinoblastoma." (PMID 37741985, 2023). "circE2F3 (hsa_circ_0075804), localized in cytoplasm, was upregulated in retinoblastoma, and overexpression of circE2F3 promoted the proliferation of retinoblastoma by increasing E2F3 expression." (PMID 33643900, 2020). "circE2F3 bound with HNRNPK and facilitate HNRNPK-mediated mRNA stability of E2F3, improving the stability of E2F3 mRNA in retinoblastoma." (PMID 33643900, 2020). "Previous studies have revealed increased E2F3 expression in different types of tumors, such as lung, prostate, bladder and retinoblastoma." (PMID 32669100, 2020). "A series of canonical pathways, including those involved in Rb (Retinoblastoma)/E2F cell cycle (Rb, E2f2, E2f3, E2f5, Cdk6, DHFR), Notch (Dll1, Notch 2, Jag1), Wnt (Wnt, Axin2, Wisp2/Ccn5) and NF-κB (Ikbip) were found to participate in this network." (PMID 30742662, 2019). "DEK is localized in chromosome 6p, the region frequently observed to be amplified in retinoblastoma, which also encompasses another oncogene (E2F3)." (PMID 29914080, 2018). "For example, results showed progressive gain of MYCN and E2F3 as well as high expression of p16INK4a and p130 in retinomas compared to a low expression in retinoblastoma." (PMID 29124525, 2017). "In RB1-mutated retinoblastoma, all three activating E2Fs were significantly upregulated: E2F1 (FC = 1.86, P = 2.56E-03), E2F2 (FC = 2.84, P = 2.31E-04), and E2F3 (FC = 3.72, P = 2.18E-10)." (PMID 25161863, 2014). "Both DEK and E2F3 have been identified as over-expressed transcripts due to chromosome 6p gains in retinoblastoma, a common pediatric malignancy." (PMID 17397536, 2007). "However, aE2Fs are essential for abnormal division of differentiating RB-null cells and removing E2F1 or E2F3 completely block retinoblastoma formation." (PMID 32071286, 2020). "Previous studies have shown that loss of E2f1 and E2f3, but not E2f5, prevents retinoblastoma formation in Rb1-deficient mice." (PMID 30220967, 2018). "However, data suggests that the transition into retinoblastoma requires further copy number changes in key genes—gain in KIF14, E2F3, MYCN and loss in DEK and CDH1." (PMID 29124525, 2017). "Also, our results support a role of E2f1 and E2f3 in retinoblastoma formation through deregulation of miRNA expression." (PMID 25338120, 2014). "KIF14 and E2F3 mRNA expression was quantified by real time PCR in 57 retinoblastoma (RB) tumors, 3 RB cell lines, and control samples that included 4 each fetal, age-matched, adult retinas." (PMID 19190782, 2009).
retinoblastoma (continued). "Hsa_circ_0075804, for example, promotes the stability of transcription factor E2F3 mRNA by binding to HNRNPK, thereby promoting retinoblastoma proliferation in an E2F3-dependent manner." (PMID 34202482, 2021). "However, the reason for E2F3 mRNA upregulation in retinoblastoma remains unclear." (PMID 32669100, 2020). "lncRNA RBAT1 is one of the most highly expressed lncRNAs in retinoblastoma (29.83-fold higher in Rb tissues than that in adjacent tissues), and RBAT1 resides on chr6p22.3, the promoter region of E2F3 gene." (PMID 32669100, 2020). "We did observe subtle elevation in the expression of DEK, NUP153, E2F3 and TTRAP and additional studies will be required to determine the functional significance of elevated gene expression in human retinoblastoma." (PMID 24509483, 2014). "Interestingly, the GEO2R and co-expression network analysis have identified three genes namely E2F3, ESR1, and UNC5D that are significantly deregulated by modified DNA methylation, mRNA and microRNA expression in Rb tumors." (PMID 35359459, 2022). "A previous study performed in retinoblastoma, a childhood cancer caused by bi-allelic loss of RB1, indicated that retinal tumorigenesis was driven by E2F1- and E2F3-transcribed genes following the lack of transcriptional repression due to RB loss." (PMID 30220967, 2018). "The expression of E2F3 and UNC5D were up-regulated and that of ESR1 was down-regulated in Rb tumor cells when compared to that in non-tumorigenic hTERT-RPE cells." (PMID 35359459, 2022).
ovarian carcinoma (26 papers, 2009 to 2025). A malignant neoplasm originating from the surface ovarian epithelium. "Also, E2F3 was confirmed to be down-regulated upon induction of miR-210 in ovarian cancer and miR-210 linked hypoxia with regulation of cell cycle and played a crucial role in ovarian cancer onset." (PMID 28947999, 2017). "In ovarian cancer cells, knockdown of miR-34a resulted in a significant increase in E2F3 expression, highlighting its role in cell cycle regulation." (PMID 40171271, 2025). "Hypoxia-driven miR-210 directly targets E2F3 to inhibit cell proliferation in various cell lines including keratinocytes, ovarian cancer cells and human embryonic kidney cells." (PMID 24586608, 2014). "Mapping OIMs and their pathways in ovarian cancer revealed interactions between several miRs and transcription factor E2F and particularly between E2F3 and miRs-148b, -124 and -34a." (PMID 23358700, 2013). "In the discovery set, SNPs in several genes were found to be associated with the risk of ovarian cancer; of these, five genes (ABL1, CCND3, CDKN1A, E2F3 and CDK2) were significant in log-additive models (P-value <0.05)." (PMID 19738611, 2009). "E2F transcription factors (E2F3), which can interact with histone acetyltransferase and induce cells to enter the cell cycle, participated in the development and progression of many tumors, such as pancreatic cancer and ovarian cancer." (PMID 34603375, 2021). "Gene copy aberrations of the miR-210 locus were very frequent in ovarian cancer, and its reduction could induce deregulation of the hypoxia response by targeting E2F3, which in turn promoted tumor development." (PMID 28947999, 2017). "In ovarian cancer, one potentially biological relevance pair (hsa-miR-145/E2F3) was identified." (PMID 28947999, 2017). "Moreover, hsa-miR-145, a microRNA that is highly down-regulated in ovarian cancer, shows significant expression anti-correlation with E2F3 in normal samples, indicating potential transcriptional repression by hsa-miR-145 in normal cells but loss of this function in tumours." (PMID 22452920, 2012). "In the E2F family of transcription factors, E2F2, E2F3, E2F4, and E2F8 expression is increased and may play oncogenic roles in ovarian carcinoma, and exert the same effects as E2F1." (PMID 28146423, 2017).
pancreatic cancer (26 papers, 2015 to 2026). "To elucidate the molecular mechanisms underlying the involvement of miR-573 in pancreatic cancer, we used bioinformatics analysis to predict that E2F3 is a putative target gene for miR-573." (PMID 33854603, 2021). "miR-217 down-regulation in pancreatic cancer was associated with the elevation of E2F3 gene a transcription factor family, which plays an important role in cellular proliferation, apoptosis, and differentiation." (PMID 32232006, 2020). "In a recent transcriptome-wide association study, the expression level of E2F3 was identified as one of 19 genes with significant pancreatic tumor association and pancreatic cancer progression." (PMID 32232006, 2020). "For example, overexpressed LINC00857 regulates the expression of E2F3 by binding to Mir-150-5p, ultimately promoting the tumogenesis and poor outcome of pancreatic cancer." (PMID 35676619, 2022). "The results demonstrated that the expression level of E2F3 displayed a significant correlation with the tumor stage in patients with pancreatic cancer." (PMID 33854603, 2021). "Our results confirmed that E2F3 expression was significantly upregulated in pancreatic cancer tissues and cell lines." (PMID 33854603, 2021). "In the current study, we analyzed the expression of miR-573 and E2F3 in pancreatic cancer tissues and determined their role in the progression of pancreatic cancer." (PMID 33854603, 2021). "In conclusion, this study illustrated that miR-573 functions as a tumor suppressor and can negatively regulate E2F3 to inhibit cell proliferation and invasion capacity in pancreatic cancer." (PMID 33854603, 2021). "The Kaplan-Meier analysis showed that E2F3 displayed a significant correlation with the overall survival of patients with pancreatic cancer." (PMID 33854603, 2021). "Meanwhile, LINC00857 modulates E2F3 expression by binding to miR-150-5p, ultimately promoting tumorigenesis in pancreatic cancer." (PMID 35047414, 2021). "Previous study suggested that circCDR1as was overexpressed in pancreatic cancer and promoted the proliferation, migration and invasion of pancreatic cancer cells by regulating E2F3 expression via functioning as sponge for miR-432-5p." (PMID 34906151, 2021). "We observed a significantly down-regulated expression of E2F3 in pancreatic cancer cells that were transfected with E2F3 siRNA." (PMID 33854603, 2021). "Knockdown of circRHOT1 expression significantly inhibited proliferation as well as invasion, and it promoted apoptosis of pancreatic cancer cells via the regulation of E2F3 through the targeting of miR‐125a‐3p." (PMID 32697386, 2020). "E2F3 knockout elevated the colony formation ability of pancreatic cancer cells after radiation, and transfection of miR-194-5p mimics didn’t further enhance the ability." (PMID 32228703, 2020). "Previous investigations identified HMGA2 and E2F3 as two of the eight key regulator hubs of pancreatic cancer." (PMID 32228703, 2020). "E2F3 expression was inhibited by miR-194-5p mimics and miR-194-5p stably overexpression in pancreatic cancer cells, while slightly elevated by miR-194-5p inhibitor." (PMID 32228703, 2020). "Hu Q. and colleagues demonstrated that some of the molecular targets that are regulated by miR-34a in pancreatic cancer are E2F3 (E2F transcription factor 3), Bcl-2, c-MYC and cyclin D1." (PMID 27187371, 2016). "Conspicuously, we notice that 5 genes (CDK6, E2F3, CCND1, SMAD4 and CDKN1B) are associated with cell cycle, colorectal cancer, pancreatic cancer, chronic myeloid leukemia, and small cell lung cancer in the cluster of Group A." (PMID 26221171, 2015). "Interestingly, it was described that the overexpression of miR-210-3p was reported in lung, ovarian, and pancreatic cancer cells, which directly targets E2F3, linking hypoxia with the regulation of the cell cycle." (PMID 40430074, 2025). "The CCK-8 assay showed that E2F3 siRNA substantially inhibited pancreatic cancer cell growth." (PMID 33854603, 2021).